CDK5 (cyclin dependent kinase 5)
Diseases named in the same sentence as CDK5 in open-access papers (continued):
Sharing a sentence is not in itself a finding about the gene and the disease.
cancer (continued). "Like Cdk5, ubiquitin ligases are prominent players in nervous system development, function and disease, and have important roles in cancer." (PMID 35421092, 2022). "Our previous studies have reported that CDK5 plays essential roles not only in the CNS, but also in aspects of cancer, including cancer cell proliferation, apoptosis, and metastasis." (PMID 34207842, 2021). "Post-translational modifications (PTMs) of Cyclin-dependent kinase 5 (CDK5) have emerged as important regulatory mechanisms that modulate cancer development in patients." (PMID 35006426, 2021). "These examples partially explain the co-occurrence of CDK5 and p35 frequently observed in cancer, more upstream regulators should be further investigated." (PMID 35006426, 2021). "Currently, emerging types of PTM on CDK5 were identified, and were found to be involved in a wide range of cellular processes in cancer." (PMID 35006426, 2021). "Considering the oncogenic role of CDK5 in cancer, targeting the ATP binding of CDK5 and CDK5-p35 interaction is currently the two major strategies to suppress CDK5 activity, which has been used in preclinical trials of drugs for several types of tumors." (PMID 35006426, 2021). "As a proline-directed kinase, CDK5-mediated phosphorylation signaling cascade exhibits chief effect on multiple cancer progression." (PMID 35006426, 2021). "Many traditional chemotherapeutic agents are DNA damage stimulators, for instant, ionizing radiation and topoisomerase inhibitors can enhance the activity of CDK5 in cancer cells." (PMID 35006426, 2021). "Patients with higher Cdk5 expression exhibit worse clinical outcomes whereas blocking Cdk5 activity confers protection in cellular and animal models of cancer." (PMID 34814918, 2021). "Cyclin-dependent kinase-5 (CDK5) is a proline-directed serine/threonine kinase that play a key role in cancer progression." (PMID 34925377, 2021). "Recently, it has even been proposed to treat proteins that target CDK5 as possible biomarkers for some cancers." (PMID 33805800, 2021). "Although the role of CDK5 was initially thought to be restricted to neuronal development, a growing amount of evidence demonstrates that CDK5 also plays a vital role in cancer." (PMID 33924599, 2021). "Collectively, CDK5-mediated phosphorylation cascade is critical for tumor metastasis, suggesting that targeting CDK5 is a promising strategy for preventing cancer spread." (PMID 35006426, 2021). "In past decades, the role of CDK5 in cancer development was emerging, which involves in cancer metastasis, proliferation, angiogenesis and chemoresistance." (PMID 35006426, 2021). "During cancer progression, CDK5 serves as an oncogene to promote cell proliferation, migration and invasion." (PMID 35006426, 2021). "In various cancers, Cdk5 overexpression correlates with poor prognosis, tumor proliferation, migration, and invasion." (PMID 34680167, 2021). "CDK5 phosphorylation and CDK5-mediated phosphorylation events were reported to play critical roles in degenerative neurological diseases and cancer." (PMID 35006426, 2021). "In this review, we discussed the role of PTMs on CDK5-mediated signaling cascade, and their possible mechanisms of action in malignant tumors, as well as the challenges and future perspectives in this field." (PMID 35006426, 2021). "Our previous studies reported that cyclin-dependent kinase 5 (CDK5) plays a crucial role in cancer progression, including MTC." (PMID 34207842, 2021). "The results show that in almost all cancer cell lines tested, including the cell lines described in S5 Table, genetic loss of CDK3 and CDK5 has a minimal impact on cell viability." (PMID 32645016, 2020). "It will also be important to use tissue-specific Cdk5 knockout mice in conjunction with mouse models of different pathological conditions (such as cancer) to conclusively resolve the role of CDK5 in physiology and in disease states." (PMID 31910742, 2020).
cancer (continued). "Depletion of CDK5 or inhibition of its activity in several in vitro cultured cancer cell lines resulted in reorganization of microtubules and the loss of cell polarity." (PMID 31910742, 2020). "Cyclin-dependent kinase 5 (CDK5), which belongs to the protein kinase family, regulates neuronal function but is also associated with cancer development and has been proposed as a target for cancer treatment." (PMID 33396266, 2020). "In this review, we summarise the normal function of CDK5, its role in cancer development, a potential CDK5-mediated tumorigenesis pathway, and potential therapeutic options." (PMID 33396266, 2020). "We hope that this review can provide a reliable platform for future research about CDK5 as a target for cancer treatment." (PMID 33396266, 2020). "In pathological conditions, such as cancer or neurodegenerative diseases, CDK5 cofactors are cleaved by calpain that removes the first 98 and 100 amino acids, producing p25 and p29, respectively." (PMID 32708903, 2020). "It has been reported that CDK5 was activated in cancer cells or tissues exposed to conventional DNA-damaging therapies including ionizing radiation (IR) or genotoxic agents." (PMID 32708903, 2020). "There are limited evidence regarding the impact of CDK5 on inflammation related to cancer development." (PMID 33396266, 2020). "The pathologic changes of CDK5 and PPARγ in a various metabolic diseases and cancer have been well addressed." (PMID 32054125, 2020). "CDK5 is also involved in various cancers; therefore, clinical trials on roscovitine have been conducted in patients with cancer." (PMID 33343298, 2020). "In contrast with these findings, several groups reached an opposite conclusion, namely that CDK5 inhibits cancer cell motility." (PMID 31910742, 2020). "The expression levels of CDK5 and cyclin I are higher in cisplatin-resistant cancers compared to cisplatin-sensitive ones and correlate with worse survival." (PMID 31910742, 2020). "We expect that our review helps researchers to develop CDK5 inhibitors as treatments for refractory cancer." (PMID 33396266, 2020). "Cdk5 functions in the development and progression of cancers through modulation of key pathways such as DNA repair and cellular migration." (PMID 32352232, 2020). "This was unexpected but supports differential physiology and roles of Cdk5 in normal and cancer cells, and calls for more comprehensive investigations on the function of Cdk5 in mitochondrial calcium dynamics in normal and disease conditions." (PMID 32024968, 2020). "CDK5 is overexpressed in various cancer, and this upregulation has been proposed to facilitate tumour proliferation and metastasis." (PMID 33396266, 2020). "Cdk5 can influence cellular migration in cancer, such as phosphorylation of FAK, promoting the formation of F‐actin bundles to facilitate epithelial to mesenchymal transition and motility." (PMID 32352232, 2020). "Butyrolactone I is a poly-CDK modulator significantly inhibiting CDK1 and CDK5 and has been considered as an anti-cancer drug candidate." (PMID 32054125, 2020). "CDK5/p25 was also involved in cancer cell migration, but one of the most interesting roles of CDK5 in oncogenesis is its potential implication in DNA repair and drug resistance." (PMID 32708903, 2020). "We present the influence of CDK5 on cancer to shed light on the potential role of CDK5 in the tumorigenesis pathway." (PMID 33396266, 2020). "We look forward to the day that the development of CDK5 specific inhibitors through many studies will be successful, and it will become a therapeutic agent for various refractory cancers." (PMID 33396266, 2020). "If it becomes clear that CDK5 promotes cancer development and progression, the development of CDK5 specific inhibitor is expected to accelerate further." (PMID 33396266, 2020). "Recently, increasing evidence suggests a role of cyclin-dependent kinase 5 (CDK5) in cancer progression." (PMID 32708903, 2020).
cancer (continued). "In this review, we mentioned the role of CDK5 in normal cells and the latest findings that CDK5 contributes to ten hallmarks of cancer and cancer-nerve connections." (PMID 33396266, 2020). "CDK5 has also been identified to play important roles in processes such as cell death and proliferation, angiogenesis, migration of epithelial and cancer cells, inflammation, myogenesis, glucose metabolism, and insulin secretion in non-neuronal cells." (PMID 31698798, 2019). "In many cancers Cdk5 inhibition or Cdk5 knockdown is shown to increase cytotoxicity and restore chemotherapeutic sensitivity." (PMID 30899038, 2019). "In this study, we explored the CDK5-mediated phosphorylation of USF2 as a regulatory mechanism, which can cause functional alterations of USF2 in cancer." (PMID 31013770, 2019). "The investigation of CDK5 function in extra-neuronal tissues is increasing as well, especially in cancer research." (PMID 31311512, 2019). "Recent studies have revealed that CDK5 suppressed the activities of several cell cycle inhibitors such as p21 and p27, and leading to the over proliferation of cancer cells." (PMID 31311512, 2019). "CDK5 knockdown or inhibition has been documented to be an anticancer agent since and is generally dysregulated in various cancer cells." (PMID 31698798, 2019). "Our results suggest that CDK5 decreases p21CIP1 protein levels by reducing p21CIP1 protein stability via proteasome-dependent degradation in cancer cells." (PMID 31395805, 2019). "In recent years, an increasing number of studies have focused on CDK5 and its substrates in cell cycle regulation and cancer." (PMID 31272499, 2019). "Our model used SH-SY5Y cells which are cancer/tumor cells; however, the complicated roles of Cdk5 in cancer, its upregulated expression, including the function of p25 activator, have not yet well understood." (PMID 30911317, 2019). "The western blot assay also showed that the protein level of CDK5 were relatively higher in normal tissues compared with the cancer tissues." (PMID 31311512, 2019). "In contrast, limited studies with cancer cells have shown that CDK5 promotes survival and proliferation." (PMID 31534152, 2019). "Previous study reported that Cdk5 contributes to cancer proliferation, migration, and chemotherapy resistance." (PMID 30911317, 2019). "In recent years, an increasing number of studies have shown that elevated expression of cyclin dependent kinase (Cdk5) contributes to the oncogenic initiation and progression of many types of cancers." (PMID 31614664, 2019). "Recently, emerging evidence showed that CDK5 played an important role in cancer tumorigenesis and progression." (PMID 31311512, 2019). "Although most of the identified CDK5 functions in cancer biology are oncogenic, opposite results were shown in gastric cancer." (PMID 31395805, 2019). "Together, these data suggest that phosphorylation of USF2 by CDK5 can promote cancer cell proliferation and migration." (PMID 31013770, 2019). "The CDK5-mediated USF2 phosphorylation promotes USF2 protein stability at least in three different cancer cell lines—PC3, HepG2, and MDA-MB-231." (PMID 31013770, 2019). "While some examples below highlight neurodegenerative pathways as examples of inactivation by phosphorylation, further cancer-focused work needs to be undertaken to extend these mechanisms as both Cdk5 and LRRK2 activity have been implicated in cancer." (PMID 30678096, 2019). "Recently, it has been reported that CDK5 plays important roles in regulating various biological and pathological processes, including cancer progression." (PMID 31395805, 2019). "Aberrant CDK5 activity plays a critical role in the growth and propagation of multiple forms of cancers." (PMID 31842413, 2019). "We found that the CDK5 expression was significant lower in primary cancer tissues compared with adjacent normal tissues in TCGA (p < 0.0001)." (PMID 31311512, 2019).
cancer (continued). "Outside of the brain, CDK5 has been recently found to participate in several pathological conditions, such as cancer, diabetes, inflammation, and senescence." (PMID 31272499, 2019). "This study not only corroborates these studies but further advances our knowledge of the role of CDK5 in cancer." (PMID 31488827, 2019). "Cyclin-dependent kinase 5 (CDK5), a generally dysregulated protein in various carcinomas, can mediate c-MYC phosphorylation at Ser-62 site." (PMID 31496920, 2019). "A recent review article outlined in detail the contributions of CDK5 to many types of cancer, supporting its potential as a novel target for cancer therapy across many tumor types." (PMID 29435174, 2018). "A variety of strategies have been developed for interrupting pathological CDK5 activity, and are in clinical trials in cancers." (PMID 29535807, 2018). "The effects of disrupting the localization of Cdk5 by drugs reveal a novel mechanism to limit its pathological signalings in cancer cells." (PMID 28288624, 2017). "In general, while a correlation exists between CDK5 mRNA and protein levels, this does not hold for p35, suggesting a different regulation of p35 protein translation between cancer and normal cells." (PMID 28640256, 2017). "Cdk5 is considered as a potential biomarker in different cancers and a promising target for cancer treatment." (PMID 28288624, 2017). "Taken all together, Cdk5 participates in tumorigenesis, progression and metastasis of different cancers through various signaling pathways, and its inhibition and knockdown have been proven to be effective in restraining cancer cell progression." (PMID 28288624, 2017). "Recent studies show that Cdk5 participates in a series of biological and pathological processes in non-neuronal cells, and is generally dysregulated in various cancer cells." (PMID 28288624, 2017). "The inhibition or knockdown of Cdk5 has been proven to play an anti-cancer role through various mechanisms, and can synergize the killing effect of chemotherapeutics." (PMID 28288624, 2017). "Increased levels of CDK5 target proteins are being considered as possible biomarkers of specific cancers." (PMID 28077789, 2017). "Taken together, these findings indicated that CDK5 is involved in numerous steps during cancer progression." (PMID 29312535, 2017). "CDK5 has been well established as centrally involved in regulating migration of neuronal progenitor cells during brain development in embryogenesis, whereas extraneuronal reactivation of CDK5 in malignant tumors has only recently been recognized." (PMID 28530703, 2017). "The emerging knowledge of the roles of Cdk5 in cancer indicates that it is a potential biomarker for diagnosis and prognosis prediction for cancer." (PMID 28288624, 2017). "The other interesting CDK protein in the shared part is CDK5, which has multiple roles in some tissues with relevance to cancers." (PMID 28241745, 2017). "Though Cdk5 is generally up-regulated in most types of cancer, it has also been reported down-regulated in certain types of cancer." (PMID 28288624, 2017). "Cdk5 is reported to be over-expressed or hyperactivated in various cancer tissues and tumor cell lines." (PMID 28288624, 2017). "There were a few researches of the relationship between CDK5 and clinical factors in the patients with cancers." (PMID 26860827, 2016). "As expected, CDK5 controlled a cluster of genes and signaling pathways related to cancer proliferation and metastasis." (PMID 27735944, 2016). "Nevertheless, inhibition by small molecules inhibiting Cdk5 and additionally Cdk1, Cdk2, Cdk7, and Cdk9 have shown promising effects in cancer/angiogenesis." (PMID 26755662, 2016).
cancer (continued). "In summary our data set the stage for Cdk5 as a drugable target to inhibit Notch-driven angiogenesis condensing the view that Cdk5 is a promising target for cancer therapy." (PMID 26755662, 2016). "Cyclin-dependent kinase 5 (CDK5) is an atypical CDK which plays a vital role in several cancers via regulating migration and motility of cancer cells." (PMID 26860827, 2016). "CDK5 also regulates cell proliferation by alterant expression and its downstream signaling pathways, especially in cancer cells." (PMID 26860827, 2016). "The results of the studies showed that CDK5 was greatly related to proliferation, migration, and motility of cancer cells." (PMID 26860827, 2016). "Up to date, there has been a growing number of evidence that CDK5 has an important effect on cancer progression." (PMID 26860827, 2016). "Appropriate amount of nestin enhances CDK5 function to suppress Rac1 and excessive nestin/CDK5 participates in multiple oncogenic pathways to promote cancer invasiveness." (PMID 25371063, 2015). "Gene expression array analysis from The Cancer Genome Atlas (TCGA) and from Oncomine (a Cancer Microarray database), suggest that CDK5 mRNA is elevated in at least 30% cases." (PMID 26146988, 2015). "CDK5 plays a role in many neurodegenerative diseases and cancers by phosphorylating the actin regulatory protein caldesmon." (PMID 26160836, 2015). "The cyclin-dependent kinase 5 (CDK5) is reported to contribute to cancer metastasis by regulating epithelial-mesenchymal transition (EMT)." (PMID 26690371, 2015). "We and others subsequently showed that CDK5 plays an important role in cancer development and metastasis." (PMID 24841903, 2014). "Our previous results and other reports both suggest that physiological regulation/activation of Cdk5 contributes to the maintenance of cancer cell growth." (PMID 23304206, 2012). "This threshold was met in at least one cancer cell line by 39 (52%) kinases and by 23 kinases in at least two cell lines, including CDK5, CSK, LYN, RSK2 and YES." (PMID 22277058, 2012). "On the other hand, we found that over-activation of Cdk5 by the truncated p25 generated from p35 cleavage is critical to drug-triggered apoptosis of cancer cells." (PMID 23304206, 2012). "Inspiring, we further extended the regulatory network of β‐catenin function and elucidated the intrinsic mechanism by which LIMK1 and CDK5 perform similar functions, introducing novel insights for targeted therapy of cancer treatment using CDK5 in combination with another agent." (PMID 40476449, 2025). "CDK5 can act as both an oncogene and a tumor suppressor, in different cancer types." (PMID 39800748, 2025). "However, in many cancers, this neurodevelopmental toolkit is repurposed, and aberrantly activated Cdk5 promotes proliferation, metastasis, and therapeutic resistance in diverse solid tumors." (PMID 41369365, 2025). "Additionally, TIGAR supports cancer cell survival by activating DNA repair through PPP in a CDK5-ATM-dependent signaling pathway, in response to hypoxia or DNA damage." (PMID 40076651, 2025). "Moreover, in proliferative settings, including cancer, emerging evidence indicates that Cdk5 can form a rare complex with cyclin B1, playing a role in the regulation of mitotic fidelity (see Section 4)." (PMID 41369365, 2025). "Additionally, very recent findings, published while this manuscript was under review, suggest that cyclin B1-CDK5 plays a role in ensuring mitotic fidelity, highlighting the potential of CDK5 as a cancer therapeutic target." (PMID 39800748, 2025). "Mechanistically, LIMK1 and CDK5 synergistically phosphorylate β‐catenin at S191, enhancing its phosphorylation and interaction with Nucleoporin 93, resulting in β‐catenin nuclear translocation and activation of key pathways in cancer metastasis." (PMID 40476449, 2025). "This also means that targeting CDK5 for cancer therapy might elicit unwanted neurological side effects." (PMID 39800748, 2025).